CCL21 (C-C motif chemokine ligand 21)
Diseases named in the same sentence as CCL21 in open-access papers (continued):
Sharing a sentence is not in itself a finding about the gene and the disease.
cancer (continued). "However, the button-like junction and the presence of CCL21 in LECs also open a path for cancer cells to enter lymphatic vessels." (PMID 39211044, 2024). "Significantly down-regulated genes in cancer tissue, compared to normal tissue included PLA2G2A, MUC4, PCK1, TXNIP, and genes encoding the CCR7 ligands, CCL19 and CCL21, which are lymphoid chemokines involved in the chemotaxis of lymphoid cells such as leukocytes and dendritic cells." (PMID 38505585, 2024). "Considering the similarities between trophoblasts and cancer cells, we speculated that CCL21 might also affect trophoblast invasion and migration." (PMID 36829431, 2023). "Besides, six factors had inverse causal associations with cancer, including CCL15, CCL18, CCL19, CCL20, CCL21, and CCL28." (PMID 38075694, 2023). "The chemokine CCL21 regulates immune and cancer cell migration through its receptor CCR7." (PMID 37664721, 2023). "It is tempting to speculate that the dual role of CCL21 in cancer could be represented by this pattern, where high levels is promoting TLS but a decrease in CCL21 can be favorable for therapy because that result in less stroma-mediated immune evasion." (PMID 37377898, 2023). "Thus, future studies will need to focus on understanding how Ly6Clo monocytes modulate CCL21 production and other endothelial functions in the setting of cancer." (PMID 37426658, 2023). "Modulating the function of the CCL19/CCL21/CCR7 axis may hold therapeutic potential for cancer as well as many inflammation‐related diseases, and there are several clinical trials currently underway." (PMID 35702353, 2022). "The function of lymphatic organs as the extracellular fluids flow sink; it has been assumed that interstitial fluids flow and CCL21 role in conjunction to monitor the migrating of the cancer cells to lymphatic vessels in the development of metastases of cancer." (PMID 35874608, 2022). "The MTT assay was utilized to evaluate the cytotoxicity of CCL21/IL1β on cancer cells." (PMID 36037155, 2022). "Furthermore, the results demonstrated a decrease in the survival rate and metastasization of cancer cells in the presence of CCL21 recombinant protein." (PMID 36037155, 2022). "CCL21 is a chemokine that can affect lymph node metastasis in various cancer types." (PMID 34566519, 2021). "The hypothesis tested in the current study was based on the premise that cancer cells use the same mechanism as leukocytes to extravasate blood and lymph vessels, using CCL21′s presentation by GAGs to metastasise to the lymph nodes." (PMID 34298676, 2021). "TUNEL staining results indicated that CCL21 inhibited the apoptosis of cancer cells (p < 0.05)." (PMID 34001131, 2021). "Moreover, the higher expression levels of certain TSGs, including GSTA2, CCL21, and MADCAM1, were associated with a significantly higher ITR in cancer." (PMID 32774369, 2020). "The promoter region of CCL21 had significantly higher methylation levels in 17 TCGA cancer types." (PMID 32774369, 2020). "Previous studies also showed that the expression of certain TSGs could promote antitumor immunity in diverse cancers, such as CCL21, MADCAM1, and FCER2." (PMID 32774369, 2020). "We found that the upregulated CCR7 binding to ligand CCL21 secreted by lymph node allows cancer cells to have chemotaxis toward lymph node, indicating that cancer cells of LSCC may invade to lymph node and metastasize through lymphatic metastasis." (PMID 31217907, 2019). "CCl21 protein can be used for anti-metastatic of cancer cell lines." (PMID 29276695, 2018). "Given that the primary objective of this study was to use the SIN for generating expanded populations of functional T-cells, we tested the effect of substrate-immobilized CCL21 + ICAM1 on the capacity of the expanded cytotoxic T-cells to kill ovalbumin-expressing cancer cells." (PMID 29942308, 2018). "CCL21 is a chemokine can be used for anti-metastatic of cancer cell lines." (PMID 29276695, 2018).
cancer (continued). "The aim of the present study was to investigate the expression of ccl21 in tomato leaves via agroinfiltration and effect of CCl21 that expressed in tomato leaves on the proliferation of human cancer cell line and also their migration capacity in a cultured monolayer, serving as in vitro wound model." (PMID 29276695, 2018). "Chemokine (C-C motif) ligand 21 (CCL21) is a lymphoid chemokine mainly produced by lymphatic vessels, stromal cells in the spleen and appendix, high endothelial venules in lymph nodes, Peyer's patches and some cancer cells." (PMID 27783999, 2017). "The prognostic value of CCL21 also varies with different type of cancers." (PMID 27783999, 2017). "But there is no study reporting that CCL21 can promote chemoresistance and cancer stem cell properties and the underling mechanism is not unclear." (PMID 27057280, 2016). "Furthermore the data also indicated the potential importance of developing therapeutic strategies targeting cancer stem-like cells and CCL21/CCR7 for reducing metastasis." (PMID 27505247, 2016). "Nonetheless, CCL21/CCR7 may facilitate cancer cell invasion via increasing MMP secretion and enhancing cell motility." (PMID 25798926, 2015). "Moreover, CXCL12 and a CCR7 ligand, CCL21, can induce the resistance of cancer cells to anoikis, which is a major hindrance to the metastatic spread of various types of cancer, by regulating proapoptotic Bmf and antiapoptotic Bcl-xL proteins." (PMID 24966464, 2014). "This ability forms the rationale for polymer-based CCL21 cancer immunotherapy that could program host immune cells in vivo." (PMID 24810425, 2014). "Because cell fusion has been linked to cancer metastasis and M13HS-2 and M13HS-8 were positive for CCR7 expression we thus investigated whether the CCL21/CCR7 axis could be activated in these hybrid cell lines." (PMID 23667660, 2013). "Therefore, a possible role of CCR7 in cancer development and metastasis is its association with cancers, as well as being linked to the expression of its ligands, CCL19 and CCL21." (PMID 22251626, 2012). "As hypothesized, the expression levels of CCR7 and CCL21 were significantly increased in cancer cells and cancerous tissues from patients." (PMID 22251626, 2012). "The precise roles of CCL16 and CCL21 in the endometrium are currently unknown, but there is considerable information regarding their functions in immunological disease and cancer." (PMID 17506907, 2007). "Furthermore, MUC1 inhibition suppressed cancer cell invasion induced by CCL21." (PMID 35203305, 2022). "Thus, therapeutic manipulation of CCL21 in autoimmune conditions and cancer may represent a double-edged sword approach and certainly needs further investigation." (PMID 34276690, 2021). "Indeed, despite an upregulation of CCR7 even higher than gold standard DC, alternative DC displayed a reduced migration in vitro toward its ligand CCL21 and would then have poor migration to the lymph node upon subcutaneous or intradermal injection into cancer patients." (PMID 26695182, 2015). "Therefore, the results suggest that CCR7 signaling could be activated and affect cancer cells themselves by inducing strong expression of CCL21." (PMID 22251626, 2012). "Recent studies have also shown that the chemokine receptor CCR7, which regulates lymphatic trafficking of leukocytes, including dendritic cells and T-cells, may contribute to lymph node metastasis of various cancers through interaction with its two known ligands, CCL21 and CCL19." (PMID 21172016, 2010). "CCL19, CCL21, and CCL25 promote lymphoid tissue formation, resulting in the priming and activation of effector T cell responses to cancer-specific antigens." (PMID 39235457, 2024). "In pan-cancer CAF atlas, we annotated the CAF subpopulation which highly expressed chemokines (CCL19, CCL21 and CXCL2) as inflammatory CAF (iCAF), likely to the previously reported iCAFs." (PMID 39703515, 2024).
cancer (continued). "As lymph nodes have a high expression of CCL21 (CCR7 ligand), the cancer cells with CCR7 expression become trapped and form metastasis there." (PMID 37600570, 2023). "Previous research has shown that the CCL21/CCR7 axis promotes EMT and metastasis in cancer cells by activating the MEK/ERK1/2 signaling pathway." (PMID 36829431, 2023). "CCL21 and CCL19 were highly expressed in Mel94, which assisted in immunotherapy of cancers by potentiating immune response." (PMID 35646893, 2022). "Our team discovered that cancer-originated DNA can activate the CXCL12-CXCR4 and CCL21-CCR7 axes in HCC cells, while sinoline treatment reduced the expressions of CXCL12, CXCR4, CCL21, and CCR7 in HCC cells." (PMID 35860597, 2022). "CC chemokine ligand 21/chemokine receptor 7 (CCL21/CCR7) facilitates growth and metastases of a variety of cancers." (PMID 35860597, 2022). "The chemokine C-C motif ligand-21 (CCL21) and the protein CD9 are amongst the many proteins and chemokines that play a role in cancer cell migration." (PMID 35103937, 2022). "Potential activity of purified CCL21/IL1β in stimulating the proliferation and migration of MCF7 cancer cell line was investigated using the wound healing method." (PMID 36037155, 2022). "The results of this study revealed that GM-CSF + CD40L + CCL21 vaccination induced abundant tumor-infiltrating lymphocytes in tumors, which suggested the benefit of CD40 blockade in cancer treatment." (PMID 35453676, 2022). "In ‘trans-cancer’ migration assays, the presence of E0771-SULT cells in Matrigel significantly reduced CCL21-induced T-cell migration as compared with that of E0771-MOCK." (PMID 35094065, 2022). "Analyses of gene and protein expression based on inflammation and carcinogenesis suggested that the decreases in CCL21 and BTLA are important in cancer chemoprevention by Fx." (PMID 34948416, 2021). "TLS in other cancers have been identified and defined by expression of a number of chemokines that are involved in TLS neogenesis: CCL19, CCL21, CXCL12, CXCL13, CCL17, and CCL22." (PMID 34943886, 2021). "CCL21 was upregulated in lymphangiogenic sprouts, possibly recruiting CCR7 expressing cancer cells toward the lymphatic vessels." (PMID 34671596, 2021). "CCL21/CCR7 generally promotes the cell cycle, MAPK, JAK/STAT, NFκB, PI3K/AKT, and Rho A signals in many cancer cells with cell growth and migration." (PMID 34948416, 2021). "The chemokine receptors CCR7 and CXCR4, which are expressed by invading cancer cells, bind to secreting chemokines such as CCL21 and CXCL12, to recruit more cancer cells towards lymphatic vessels." (PMID 33172072, 2020). "The expression levels of CCL21 had a significant positive correlation with the enrichment levels of CD8+ T cells and dendritic cells in 5 and 6 TCGA cancer types, respectively (cor ≥0.3)." (PMID 32774369, 2020). "While the overexpression of CXCR4/CXCL12 is correlated with the homing of cancer cells to the liver, lung, bone marrow and lymph nodes, the overexpression of the CCR7/CCL21 axis has mainly been related to lymph node metastasis." (PMID 32340161, 2020). "Recent investigations demonstrated that SDF-1 and CCL21 chemokines through their cognate receptors CXCR4 and CCR7, signals to mTOR pathway in other cancers." (PMID 30518812, 2019). "Hypoxia promoted cancer cell production of more macrophage chemokines, and among all increased chemokines (CCL2, CCL5, CCL8, CCL19, CCL21, and CXCL1), CCL8 was the most increased according to qRT-PCR detection." (PMID 31263103, 2019). "We demonstrate that fluorescently tagged CCL19 and CCL21 permit the visualization and quantification of chemokine gradients in real time, while CCR7-expressing leukocytes and cancer cells sense the guidance cues and migrate along the chemokine gradients." (PMID 30518137, 2018). "CCR7-expressing cancer cells are also recruited by CCL19 and CCL21 to metastasize in lymphoid organs." (PMID 30518137, 2018).
cancer (continued). "The chemokine receptor CCR7 and its chemokine ligands CCL21 and, less so, CCL19, recruit circulating metastatic cancer cells to lymphatic tissue." (PMID 28841151, 2017). "Although several chemokines, such as CCL4, CCL19, CCL21, CXCL2 or CXCL12, were upregulated at the invasive border than cancer centre, expressions of their receptors were very low in PTC, except for CXCL12 receptor." (PMID 28489070, 2017). "This increased adhesion effect which was displayed after CCL21 treatment only in hypoxia, was totally inhibited upon blocking the CCR7 receptors on the MDA-MB-231 cancer cells by pre-incubation with anti-CCR7 neutralizing antibodies." (PMID 28416768, 2017). "In these malignancies, interaction of CCR7 with CCL21 drives migration and invasion of CCR7+ cancer cells into lymph nodes similarly to normal homing." (PMID 28416768, 2017). "This participates to the understanding of the CCL21/CCR7 impact on the activity and aggressiveness of cancer stem/initiating cells in the hypoxic microenvironment." (PMID 28416768, 2017). "CCL21 participates in the proliferation of CD4 T cells, kidney mesangial cells, and various cancer cells." (PMID 25798926, 2015). "It is well known that CCR7-expressing cancer cells exhibit high lymphatic invasion ability due to the chemotactic effect of its ligands CCL19 and CCL21 which predominantly expressed in lymphatic endothelial cells." (PMID 24915301, 2014). "Diverse functional studies investigating the influence of CCR7 expression and the activation by its ligand CCL21 were recently conducted, revealing that CCR7 is crucial for adhesion, migration, and invasion of CCR7-expressing malignant tumors." (PMID 21548969, 2011). "Stimulation of CCR7 by its ligand CCL21 induces migration and invasion of CCR7-expressing cancer cells." (PMID 21548969, 2011). "Pan-cancer analysis of the relationship between OBSCN expression and chemokines revealed a significant negative correlation between OBSCN expression and a variety of chemokines, including CXCL10, CXCL11, CCL11, CCL21, and CCL23." (PMID 40149008, 2025). "Moreover, the CCR7 chemokine axis, which encompasses CCL21 and CCL19, has emerged as a promising target for cancer immunotherapy, demonstrating potential as a target for therapeutic intervention." (PMID 39505867, 2024). "Researchers transplanted collagen sponge scaffolds containing LTα1β2, CCL19, CCL21, CXCL12, CXCL13, and soluble RANK ligands, which over time resulted in the development of immune-competent artificial TLSs with potential applications for cancer treatment." (PMID 39840050, 2024). "Additionally, the intricate chemokine receptor 7 (CCR7) chemokine axis, characterized by chemokine ligand 21 (CCL21) and CCL19, has emerged as a promising avenue in cancer immunotherapy." (PMID 37944262, 2023). "The significant KEGG pathways are chemokine signaling pathway (CCL5, CCL18, CCL19, CCL21, CXCL12, CXCL14, CXCL13), ​​NF-kappa B signaling pathway (CCL19, CCL21, CXCL12), intestinal immune network for IgA production (TNFRSF17, CXCL12), pathways in cancer (IGF1, CXCL12)." (PMID 35486660, 2022). "Our findings suggest that the CCL21/CCR7 axis, BTLA, TME, EMT, and adhesion may be key regulators of cancer chemoprevention in C57BL/6J mice receiving allogenic and orthotopic transplants of KMPC44 cells by Fx administration." (PMID 34948416, 2021). "The discovery that cancer cells overexpress C-C Chemokine receptor 7 (CCR7), which directs them to organs that express their ligands CCL21 and CCL19, led to an increase in reports confirming that chemokine receptors were present in a non-random manner in many other cancers." (PMID 32340161, 2020). "However, the same chemokines recruit cells that promote the development of cancer, for example CCL17/TARC and CCL22/MDC, CCL20/LARC or CCL19/ELC and CCL21/SLC." (PMID 32781743, 2020).
cancer (continued). "Similarly, LECs express a high level of the CCR7 ligands CCL19 and CCL21, and COX-2-induced upregulation of CCR7 in cancer cells promotes the migration of cancer cells toward LECs, enhancing lymphatic invasion." (PMID 33203856, 2020). "Notably, TNFAIP8L3, CCL14, CX3CR1, CCL21, IL1R1, and IL33 had higher expression levels in the lower-TMB subtype of at least 13 cancer types, while had higher expression levels in the higher-TMB subtype of at most 2 cancer types." (PMID 30634925, 2019). "On the contrary, the high CCR7 expression on IFN-DCs did not associate with the induction of CCL21 transcripts on cancer cells, suggesting a minor role of the CCR7/CCL21 axis for the movement and function of IFN-DCs under these conditions." (PMID 28439087, 2017). "In comparison to normoxia we showed that CCL21 production is not increased upon hypoxia either in CAFs or in carcinoma cells." (PMID 28416768, 2017). "But no study has indicated the role of Snail in CCL21 promoted chemoresistance and cancer stem cell property in HCT116 cells." (PMID 27057280, 2016). "CCL21 and CXCL10 transcript levels were comparable between the cancer and unaffected tissues." (PMID 27517754, 2016). "CCL21 could promote chemoresistance in cancer cell by its receptor CCR7; hence, CCR7 may be seen as a target in the future cancer therapy." (PMID 27057280, 2016). "Considering MUC1-C as an oncogene in cancers, we assumed that the increasing expression of MUC1-C may be responsible for the migration and invasion induced by CCL21." (PMID 26667143, 2015). "Towards reinforcing adoptive cancer immunotherapy, a ‘Synthetic Immune Niche’ (SIN) strategy was recently developed by Adutler-Lieber et.al., based on the stimulation of T-cells by surfaces, coated with the chemokine C-C motif Ligand 21 (CCL21) and the Intercellular Adhesion Molecule 1 (ICAM-1)." (PMID 36937426, 2023). "We hypothesize that the Ly6Clo nonclassical monocytes that patrol the vasculature elicit CCL21 production by endothelial cells, which in turn stimulates T cell recruitment to lung and lung-draining lymph nodes in response to cancer." (PMID 37426658, 2023). "Additional studies have described cancer immunocytokine therapy incorporating tissue factor, IL-4, IL-3, granulocyte colony-stimulating factor (G-CSF), IL-1β, IL-6, IL-13, IL-17, IL-7, vascular endothelial growth factor (VEGF), C-C motif chemokine ligand 21 (CCL21), and 4-1BBL." (PMID 33803078, 2021). "For example, CCL21 (CC chemokine ligand 21) and CCL19 (CC chemokine ligand 19) recruit antigen-presenting dendritic cells and naïve T-cells to the lymph nodes and are thought to play a role in lymph node metastasis of CCR7 (CC chemokine receptor 7)-expressing cancer cells." (PMID 28841151, 2017). "Likewise, CCL19 was not required for dendritic cell migration from the skin, full dendritic cell maturation and efficient T lymphocyte priming suggesting that CCL21 is the critical CCR7 ligand regulating dendritic cell homeostasis and function in vivo, which may also belong to cancer metastasis." (PMID 23667660, 2013). "Data of Wiley and colleagues further indicate that CCL21, and not CCL19, preferentially mediates lymph node metastasis of cancer cells." (PMID 23667660, 2013). "Surprisingly, despite a clear activation of the non-canonical NF-κB pathway in the cancer cells tested, they did not secrete the chemokines CXCL12, CXCL13, CCL19 and CCL21, known to be induced as a consequence of activation of this signaling pathway upon LTβR stimulation of other cell types." (PMID 39215104, 2024).